PSEN1 (presenilin 1)
Diseases named in the same sentence as PSEN1 in open-access papers (continued):
Sharing a sentence is not in itself a finding about the gene and the disease.
head and neck squamous cell carcinoma (3 papers, 2020 to 2023). A squamous cell carcinoma that arises from any of the following anatomic sites: lip and oral cavity, nasal cavity, paranasal sinuses, pharynx, larynx, and salivary glands. "A study proved that dysregulation of PSEN1 expression is implicated in dismal prognosis of patients with head and neck squamous cell carcinoma." (PMID 35096015, 2021). "A previous study 56 found that PSEN1 expression was significantly up-regulated in both head and neck squamous cell carcinoma (HNSCC) cell lines and tissue samples, and was associated with poor prognosis and radiotherapy resistance in HNSCC." (PMID 37928268, 2023). "Knockdown of lncRNA bladder cancer associated transcript 1 (BLACAT1) accelerated apoptosis of head and neck squamous cell carcinoma cells (HNSCC) by positively regulating expression of presenilin 1 protein (PSEN1)." (PMID 32585857, 2020).
hippocampal atrophy (3 papers, 2018 to 2024). "The lack of hippocampal atrophy in our analysis may therefore reflect the asymptomatic to early symptomatic stage of PSEN1 E280A mutation carriers, in which there may be a transition from a developmental increase to a neurodegenerative decrease in hippocampal volume." (PMID 38760448, 2024).
Hypertension (3 papers, 2018 to 2025). The presence of chronic increased pressure in the systemic arterial system. "The post‐200 PSEN1 carrier group had a similar prevalence of hypertension compared to the NC group, so in our cohort having hypertension did not entirely explain the more severe SVD markers in this group." (PMID 38380882, 2024).
Insulin resistance (3 papers, 2016 to 2022). Increased resistance towards insulin, that is, diminished effectiveness of insulin in reducing blood glucose levels. "The APP/PSEN1 mice appeared resistant to the hypoxia-mediated trend for lower insulin levels and lesser insulin resistance seen in wt." (PMID 35852609, 2022). "Examples include young adult carriers of presenilin-1 or apolipoprotein E4, and young adults with mild insulin resistance or with a maternal family history of AD." (PMID 27458340, 2016).
liver cancer (3 papers, 2021 to 2023). An epithelial or non-epithelial malignant neoplasm that arises from the liver. "Further exploration found that KK-LC-1, through interaction with presenilin-1, activates the Notch1 signaling pathway and then it plays a role in promoting the growth, migration and invasion of liver cancer, thus triggering the tumorigenesis of liver cancer." (PMID 35855340, 2022).
multiple sclerosis (3 papers, 2018 to 2025). A progressive autoimmune disorder affecting the central nervous system resulting in demyelination. "The apparent disconnect between the in vitro and in vivo effects of disrupting PSEN1 and γ-secretase support the need for stringent in vivo models as we seek to unravel the immunology of complex diseases such as multiple sclerosis." (PMID 30089166, 2018).
posterior cortical atrophy (3 papers, 2013 to 2019). Posterior Cortical Atrophy (PCA) is a rare progressive neurodegenerative disorder with a typical onset between 50-65 years of age characterized by progressive impairment of higher visual processing skills and other posterior cortical functions without any evidence of ocular abnormalities. "Here we present a patient with a clinical diagnosis of posterior cortical atrophy who harbors a novel Presenilin 1 mutation (I211M)." (PMID 23593396, 2013).
acute T-cell lymphoblastic leukemia (2 papers, 2009 to 2021). "Decreased expression of Presenilin 1 is associated with resistance of acute T-cell lymphoblastic leukemia (ALL) to gamma-secretase inhibitors (GSI)." (PMID 19602286, 2009).
apraxia (2 papers, 2023 to 2025). Apraxia is a neurological disorder characterized by the inability to perform tasks or movements, despite having the desire and physical ability to perform them. "Patients with PSEN1+ presented higher frequencies of gait disorders compared to those with PSEN1−, and apraxia was more frequent with PSEN1+/APOE4+ than in the rest of the subgroups." (PMID 37958671, 2023). "The PSEN1+ group presented higher frequencies of gait disorders compared to PSEN1− group, and apraxia was more frequent with PSEN1+/APOE4+ than in the rest of the subgroup." (PMID 37958671, 2023).
asphyxia (2 papers, 2021 to 2023). A state of general hypoxia and hypercapnia (abnormally elevated carbon dioxide (CO2) levels in the blood), resulting in acidosis, which affects all tissues in the body. "After perinatal asphyxia, the expression of the presenilin 1 gene in the 1–7 and 8–14 age groups was below the control values." (PMID 34067945, 2021).
chronic periodontitis (2 papers, 2021 to 2023). A chronic inflammatory process that affects the tissues that surround and support the teeth. "However, as AD is also characterized by the presence of neurofibrillary tangles, 3 × Tg-AD mice bearing mutations on presenilin 1, APP, and tau protein were employed in this study to investigate the impacts of periodontitis on AD." (PMID 36915108, 2023).
corticobasal syndrome (2 papers, 2020). Corticobasal syndrome (CBS) is a rare neurodegenerative disease characterized by multifaceted motor system dysfunctions and cognitive defects such as asymmetric rigidity, bradykinesia, limb apraxia, and visuospatial dysfunction. "Lastly, genes responsible for early onset AD (EOAD) like presenilin 1 (PSEN1) and amyloid precursor protein (APP) can give rise to atypical parkinsonism like corticobasal syndrome (CBS)." (PMID 33250855, 2020).
esophageal cancer (2 papers, 2021 to 2022). A primary or metastatic malignant neoplasm involving the esophagus. "By targeting presenilin-1 (PSEN1), miR-193a-3p could also confer 5-FU resistance of esophageal cancer cells." (PMID 34881242, 2021).
esophageal squamous cell carcinoma (2 papers, 2021 to 2024). Esophageal squamous cell carcinoma (ESCC) is a type of esophageal carcinoma (EC) that can affect any part of the esophagus, but is usually located in the upper or middle third. "In addition, when PSEN1 was overexpressed, chemotherapeutic and radiotherapeutic resistance of esophageal squamous cell carcinoma abated, thereby inducing cell apoptosis." (PMID 34568005, 2021). "The down-regulation of miR-193a-3p decreased the chemoresistance and radioresistance of oesophageal squamous cell carcinoma (ESCC) cells via the presenilin 1 (Psen1) gene." (PMID 39451223, 2024).
experimental autoimmune encephalomyelitis (2 papers, 2018 to 2025). An autoimmune demyelinating disease of the central nervous system that is produced experimentally in animals by the injection of homogenized brain or spinal cord in Freund's adjuvant. "In this study we sought to understand the functions of Presenilin 1 (PSEN1) in regulating T cell effector responses in the experimental autoimmune encephalomyelitis (EAE) murine model of MS." (PMID 30089166, 2018).
glioma (2 papers, 2021 to 2022). A benign or malignant brain and spinal cord tumor that arises from glial cells (astrocytes, oligodendrocytes, ependymal cells). "In conclusion, scutellarin and its combination with C18H17NO6, with acceptable toxicity, suppressed the proliferation and migration and induced the apoptosis of glioma, which was partly associated with the repression of PSEN1/PI3K-AKT signaling axis." (PMID 34568005, 2021). "Accordingly, we concluded that scutellarin and its combination with C18H17NO6 suppressed the proliferation/growth and migration and induced the apoptosis of glioma, in which the mechanism might be associated with the repression of PSEN1/PI3K-AKT signaling axis." (PMID 34568005, 2021). "Therefore, the PSEN1 might have been mutational in glioma cells." (PMID 34568005, 2021). "Taken together, scutellarin and its combination with C18H17NO6 might upregulate PSEN1 but abated PI3K/AKT signaling in glioma." (PMID 34568005, 2021). "On the one hand, compared with normal tissue, PSEN1 expression in glioma was downregulated." (PMID 34568005, 2021). "Moreover, immunoblotting assay also demonstrated that the PSEN1 protein level in glioma cells was less than that in normal astrocytes and neurons." (PMID 34568005, 2021). "Since PSEN1 inhibited cell proliferation and induced apoptosis by suppressing phosphatidylinositol 3−kinase/protein kinase B (PI3K/AKT) signaling, we further explored whether PI3K/AKT signaling was involved in the inhibitory effect on glioma by scutellarin and C18H17NO6." (PMID 34568005, 2021).
heart failure (2 papers, 2017 to 2023). Inability of the heart to pump blood at an adequate rate to meet tissue metabolic requirements. "PSEN1 knockout mice with heart failure presented lower calcium levels in the SR when compared to the wild-type mice with heart failure." (PMID 37176125, 2023). "DCM may not be related to impaired APP cleavage by gamma secretase, suggesting that PSEN1 (and PSEN2) could impact heart failure through an amyloid-independent mechanism." (PMID 37176125, 2023).
hepatocellular carcinoma (2 papers, 2021 to 2023). A malignant tumor that arises from hepatocytes. "Conversely, it is downregulated and abates 5-FU resistance through the miR-193a-3p/PSEN1 axis in hepatocellular carcinoma." (PMID 34844630, 2021).
hyperparathyroidism (2 papers, 2025 to 2026). Hyperfunction of the parathyroid glands resulting in the overproduction of parathyroid hormone. "Additionally, PTH was only minimally elevated in 8‐month PSEN1 KI mice and not changed in younger PSEN1 KI mice, ruling out hyperparathyroidism as a likely cause of low bone mass." (PMID 41496612, 2026).
Impaired glucose tolerance (2 papers, 2016 to 2026). An abnormal resistance to glucose, i.e., a reduction in the ability to maintain glucose levels in the blood stream within normal limits following oral or intravenous administration of glucose. "PSEN1 mutations have been associated with peripheral dysfunctions, including alterations in metabolites and impaired glucose tolerance." (PMID 41457719, 2026). "Male APP/PSEN1, Sorcs1 -/-, and Sorcs1 -/- x APP/PSEN1 mice continued to display impaired glucose tolerance compared to WT mice." (PMID 26916443, 2016).
memory (2 papers, 2023 to 2025). The activities involved in the mental information processing system that receives (registers), modifies, stores, and retrieves informational stimuli. "In animal models, using an amyloid precursor protein (APP)/presenilin-1 (PS-1) double transgenic (TG) mouse model of AD, treatment with QUET attenuated memory impairment, decreased the number of β-amyloid (Aβ) plaques and up-regulated the cerebral anti-apoptosis B-cell lymphoma (Bcl)-2 protein." (PMID 37511284, 2023).
neuropathy (2 papers, 2025). A disorder affecting the nervous system that manifests with pain, tingling, numbness, and/or muscle weakness. "The accumulation of Aβ/APP-CTF promotes neuropathy by eliciting endosomal abnormality and Rab5 overactivation and compromising lysosomal calcium stores through inhibition of lysosome-ER contacts in PSEN1 knockout or mutant mouse neurons or human iNeurons45, 69–71." (PMID 37034684, 2025). "The accumulation of Aβ/APP-CTF promotes neuropathy by eliciting endosomal abnormality and Rab5 overactivation, and compromising lysosomal calcium stores through inhibition of lysosome–endoplasmic reticulum contacts in PSEN1-knockout or mutant mouse neurons, or human induced neurons." (PMID 40140603, 2025).
proteinopathy (2 papers, 2025). "Stepwise elimination of non-significant variables indicated 3 attributes that predicted an earlier onset age: possession of a PSEN1 mutation, possession of an APOE- ε4 genotype, and presence of TDP-43 proteinopathy." (PMID 39656832, 2025).
synucleinopathies (2 papers, 2018 to 2025). "The identification of a molecular interaction between presenilin 1 (PS1), encoded by the PSEN1 gene, and αSyn was suggested to in part explain the clinical and pathophysiological overlaps between AD and synucleinopathies like DLB." (PMID 30477568, 2018). "Furthermore, a molecular interaction of PSEN1 and αSyn may explain the clinical and pathophysiological overlap between synucleinopathies, including DLB and some forms of AD." (PMID 40868991, 2025).
Adult onset (1 paper, 2021). Onset of disease manifestations in adulthood, defined here as at the age of 16 years or later. "EOfAD is an adult-onset disease and heterozygosity for EOfAD mutations in human PSEN1 allows (as far as we know) normal embryo development." (PMID 33761877, 2021).
Anosmia (1 paper, 2021). An inability to perceive odors. "Overall, APP/PSEN1-Tg animals seem not to present a complete anosmia, although it seems that they display a loss of discrimination between odours, so this possible hyposmia together with working memory impairments could explain the indiscriminate investigation that transgenic mice display." (PMID 33795014, 2021).
atherosclerosis (1 paper, 2025). A disease characterized by the build-up of fatty material and calcium deposition in the arterial wall resulting in partial or complete occlusion of the arterial lumen. "We also sought to determine the predictive variables for the prevalence of CAA (NPAMY) or circle of Willis atherosclerosis (AVAS), as both of these pathologies are enriched in those with a PSEN1 mutation." (PMID 39656832, 2025).
Autoimmunity (1 paper, 2018). The occurrence of an immune reaction against the organism's own cells or tissues. "This suggests that PSEN1 expression by T cells is dispensable for the development of autoimmunity." (PMID 30089166, 2018). "In vivo GSI treatments and PSEN1 deletion had modest effects on autoimmunity in the EAE model." (PMID 30089166, 2018).
bladder tumor (1 paper, 2021). "Furthermore, IHC analysis of bladder tumor tissues demonstrated decreased staining for Notch 1, Presenilin 1, Hes1 and Nicastrin in mice treated with CPX-POM." (PMID 34059639, 2021).
brain injury (1 paper, 2020). Acute and chronic (see also brain INJURIES, CHRONIC) injuries to the brain, including the cerebral hemispheres, CEREBELLUM, and brain STEM. "Recent advances in understanding the post-ischemic neuropathology have revealed dysregulation of amyloid protein precursor, α-secretase, β-secretase, presenilin 1 and 2, and tau protein genes after ischemic brain injury." (PMID 32366028, 2020). "An increase in presenilin 1 mRNA was observed in the hippocampal CA3 region and dentate gyrus in animal studies of post-ischemic brain injury." (PMID 32366028, 2020).
colon cancer (1 paper, 2022). "In the light of our findings, we propose such a model that upregulated PSEN1 in colon cancer might facilitate PD-L1 truncation via potential proteolytic processing, releasing its active C-terminal fragment which is subject to HDAC2-mediated deacetylation and subsequent nuclear translocation." (PMID 36059511, 2022). "Intrigued by the intrinsic immune suppressive microenvironment and high frequency of immune evasion of colon cancer, we postulate that PSEN1 may contribute to the regulation of PD-1/PD-L1 signaling in colon cancer, and thus investigate the relationship between PSEN1 and PD-L1 translocation." (PMID 36059511, 2022). "Furthermore we interrogated the protein levels of PSEN1 against colon cancer stages." (PMID 36059511, 2022).
diabetic retinopathy (1 paper, 2019). "During the early phase of diabetic retinopathy, 19,20-DHDP alters the distribution of presenilin 1 in lipid rafts of the cell membrane, thereby preventing interaction between presenilin 1 and cadherins and disrupting endothelial cell to pericyte and endothelial cell-to-cell contacts." (PMID 30792659, 2019).
Erythema (1 paper, 2023). Redness of the skin, caused by hyperemia of the capillaries in the lower layers of the skin. "Various skin abnormalities, such as hyperkeratosis, abnormality of the plantar skin of the foot, palmoplantar keratoderma, subcutaneous nodules and erythema, were associated with GJA1, KRT1, KRT2, PSEN1 and INSR." (PMID 37185447, 2023).
familial hidradenitis suppurativa (1 paper, 2025). "Additionally, loss of function mutations in PSEN1, PSENEN and NCSTN all cause familial hidradenitis suppurativa, a chronic inflammatory skin condition, further supporting a putative anti-inflammatory role of γ-secretase." (PMID 40542358, 2025).
fungal infection (1 paper, 2022). "Additionally, it implies that both PSEN1 and PSEN2 play a pivotal role in the Notch signaling pathway of the human defense system against fungal infection on the AMPs―AFPs’ axis." (PMID 35216171, 2022).
glioblastoma (1 paper, 2023). The most malignant astrocytic tumor (WHO grade IV). "The down-regulation of PSEN1 could enhance the growth of glioblastoma cells, while the overexpression of PSEN1 may prevent or slow down the beta-catenin-dependent cell proliferation of glioblastoma." (PMID 37176125, 2023).
Headache (1 paper, 2022). Cephalgia, or pain sensed in various parts of the head, not confined to the area of distribution of any nerve. "In the clinical, a higher prevalence of headaches in MCs is held for different PSEN1 and APP mutations and electrophysiological features related to longer latencies of the N100, P200, N200, and P300 components, and smaller slow wave amplitudes." (PMID 35959289, 2022).
lung carcinoma (1 paper, 2017). "Interestingly, the PSEN1 D257N somatic mutation, leading to PSEN1 haploinsufficiency, has been found in lung carcinoma"." (PMID 29137240, 2017).
metachromatic leukodystrophy (1 paper, 2024). A rare lysosomal storage disorder characterized by intralysosomal accumulation of sulfatides in various tissues, leading to progressive deterioration of motor and neurocognitive function. "For instance, among genetic mutations linked to known hNDDs, examples include HTT gene mutation in HD, SOD1 in amyotrophic lateral sclerosis, PSEN1, PSEN2, and APP in AD, ARSA gene mutation in metachromatic leukodystrophy (MLD), and others." (PMID 39200370, 2024).
myocardial infarction (1 paper, 2024). Gross necrosis of the myocardium, as a result of interruption of the blood supply to the area, as in coronary thrombosis. "For example, mutations in the presenilin genes PSEN1 and PSEN2 associated with early familial AD are also associated with dilated cardiomyopathy (CM) and HF, while the ApoE4 has also been associated with ischemic heart disease, myocardial infarction (MI), and AS." (PMID 39452073, 2024).
myocarditis (1 paper, 2019). Myocarditis is a condition that is characterized by inflammation of the heart muscle (myocardium). "Collectively, CVB3-induced cleavage of NUP98 and subsequent impairment of the cardioprotective NRG1-ERBB4/PSEN1 signaling cascade may contribute to increased myocardial damage in the context of CVB3-induced myocarditis." (PMID 31396490, 2019).
osteosarcoma (1 paper, 2020). A usually aggressive malignant bone-forming mesenchymal neoplasm, predominantly affecting adolescents and young adults. "Tomatidine, up to 100 μM, without cytotoxicity, inhibited the invasion and migration capabilities of human osteosarcoma U2OS and HOS cells and repressed presenilin 1 (PS-1) expression of U2OS cells." (PMID 31941156, 2020).
pancreatic cancer (1 paper, 2018). "We measured the expression of key members of the Notch Signaling Pathway (NUMB, DTX4, DTX3L, PSEN1, APH1A, ADAM17 and EP300) in the MiaPaCa-2-miR-148a by qRT-PCR, and compared it with the basal levels of the control pancreatic cancer cell line MiaPaCa-2, expressing very low levels of miR-148a." (PMID 29464088, 2018).
prediabetes (1 paper, 2018). "For example, our group recently showed that APP/PSEN1 amyloid-depositing mice exhibit reduced hypothalamic insulin signaling and are more susceptible to aging and over-nutrition induced prediabetes." (PMID 29945658, 2018).